CCDC25 (coiled-coil domain containing 25)
Diseases named in the same sentence as CCDC25 in open-access papers (continued):
Sharing a sentence is not in itself a finding about the gene and the disease.
tumor (continued). "One of these studies reported that NET-DNA induced migration, adhesion and proliferation of tumour cells via interaction with CCDC25." (PMID 35406451, 2022). "Since C1QBP and KNG1 are supposed to be involved in the crosstalk between KLK11 and CCDC25, their role in tumor metastasis should be explored." (PMID 34067437, 2021). "Another example is the coiled-coil domain containing protein 25 (CCDC25), a protein expressed on the surface of tumor cells, that recognizes and binds the DNA molecules released by NETs." (PMID 34261496, 2021). "This A1AT-mediated upregulation of CCDC25 sensitizes tumor cells to surrounding NET-DNA." (PMID 41980200, 2026). "Moreover, in 4T1 tumors treated by radiotherapy, Ccdc25 knockdown promoted tumor regression and significantly increased the number of TUNEL+ tumor cells." (PMID 41480760, 2026). "In addition, the formation of NETs at the tumor site was somewhat inhibited after knocking down CCDC25, which explains the inhibition of tumor metastasis." (PMID 38369519, 2024). "VNP-shCCDC25 effectively blocked the downstream prometastatic signaling pathway of CCDC25 at tumor sites and reduced the formation of NETs while recruiting more neutrophils and macrophages to the tumor core, ultimately leading to excellent metastasis inhibition in the two lung metastasis models." (PMID 38369519, 2024). "In vivo, CCDC25 overexpression inhibited tumor growth and promoted apoptosis." (PMID 38570766, 2024). "The DNA component of NETs has a chemotactic effect on tumor cells by interacting with CCDC25 on the surface of tumor cells with high affinity, and DNA-CCDC25 interactions trigger intracellular signaling cascade responses that ultimately promote the migration and metastasis of tumor cells." (PMID 38369519, 2024). "NETs may directly facilitate the development of metastasis by capturing tumor cells at distant sites by interactions between NETs and the coiled-coil domain-containing protein 25 (CCDC25)." (PMID 38539330, 2024). "CCDC25 attenuates tumor growth and promotes apoptosis within the tumor tissue." (PMID 38570766, 2024). "Tumor cells sense extracellular DNA through the membrane protein CCDC25 for capture by NETs." (PMID 36788538, 2023). "The DNA component of NETs was found to act as a chemotactic factor to attract tumor cells through an extracellular DNA-sensor, CCDC25, expressed on tumor cells which subsequently activated the integrin-linked kinase (ILK)-β-parvin pathway to enhance cell motility." (PMID 34884995, 2021). "Therefore, it is reasonable to speculate that the expression or activity of prometastatic genes downstream of CCDC25 in tumor cells and the formation of NETs at tumor sites would also be affected." (PMID 38369519, 2024). "Loss of 8p involving the DLC1, CCDC25, ELP3, PROSC, SORBS3, SH2D4A genes associated with poor outcomes for HCC; in vitro and in vivo analysis indicated that the PROCS, SH2D4A and SORBS3 genes have tumor-suppressive activities and the DLC1 gene is a known tumor suppressor gene." (PMID 34103027, 2021). "In vivo, knocking out CCDC25 in MCF-7 cells that were inoculated into NOD/SCID mice significantly improved the efficacy of chemotherapy, demonstrated by the reduced tumor growth and increased proportion of CK+TUNEL+ tumor cells." (PMID 41480760, 2026). "Their DNA components bind to coiled-coil domain-containing protein 25 (CCDC25), activating the ILK-β-parvin signaling pathway, enhancing tumor cell invasiveness, and driving liver metastasis." (PMID 40568594, 2025). "As ITGA3 is a crucial protein regulating tumor EMT (epithelial-mesenchymal transition), we further confirmed that overexpression of CCDC25 suppresses EMT in ccRCC cells." (PMID 38570766, 2024). "The transmembrane protein coiled-coil domain containing 25 (CCDC25) on tumor cell membranes can bind NETs-DNA with high specificity and affinity, enabling tumor cells to sense NETs and thus promote distant metastasis." (PMID 38369519, 2024).
tumor (continued). "In this study, we effectively knocked down CCDC25 by delivering nucleic acid drugs to tumor sites through VNP, a microbial delivery system, and ultimately successfully inhibited tumor metastasis in several tumor models." (PMID 38369519, 2024). "Similarly, targeting Ccdc25 in 4T1 tumor cells also inhibited primary tumor growth, increased the number of CK+TUNEL+ tumor cells, and reduced lung metastasis." (PMID 41480760, 2026). "Western blotting was conducted to compare CCDC25 expression in tumor and non-tumorous tissues (n = 4)." (PMID 39953349, 2025). "Moreover, we employed the Tumor Immune Estimation Resource (TIMER) database and CIBERSORT algorithm to investigate the relationship between CCDC25 and the tumor immune microenvironment (TME) in HCC." (PMID 36211267, 2022). "Therefore, in the present study, CCDC25 was successfully knocked down in tumor tissues by safely delivering shCCDC25 to tumor sites via VNP, which ultimately significantly inhibited tumor metastasis and demonstrated high efficiency and low toxicity in several tumor models." (PMID 38369519, 2024). "It was recently discovered that through stimulation with DNA-NETs, CCDC25 on tumor cells could initiate the ILK-β parvin signaling pathway to remodel the intracellular cytoskeleton, which facilitates migration and adhesion of tumor cells." (PMID 36050539, 2023). "In addition, NETs may enhance the motility of tumor cells by inducing cytoskeleton rearrangement via the CCDC25-ILK signaling pathway, which may further facilitate tumor cell transmigration across the endothelium." (PMID 36050539, 2023). "Consistently, the combination of anti-CCDC25 neutralizing mAb and chemotherapy significantly reduced tumor growth and lung and liver metastasis, while NET levels were comparable in the presence or absence of anti-CCDC25 neutralizing antibody." (PMID 41480760, 2026).
CCDC25 also shares sentences with these, for which no sentence is quoted: hepatocellular carcinoma (2 papers); bladder urothelial carcinoma (1); breast tumor (1); colon adenocarcinoma (1); esophageal squamous cell carcinoma (1); lung adenocarcinoma (1); metabolic disorders (1); osteoporosis (1); pan (1); pancreatic cancer (1); prostate adenocarcinoma (1); pulmonary arterial hypertension (1); rectum adenocarcinoma (1); thyroid carcinoma (1); uterine corpus endometrial carcinoma (1).